HLMR1 (hepatic lncRNA metabolic regulator 1)
Gene: Long non-coding RNA gene on chromosome 3 (142,912,116 to 142,942,537, forward strand). Ensembl gene ENSG00000243818.
Diseases named in the same sentence as HLMR1 in open-access papers:
HLMR1 is named in the same sentence as 5 diseases in open-access papers, as found by Europe PMC text mining. Sharing a sentence is not in itself a finding about the gene and the disease. The quoted sentences say what the papers report.
Hepatic steatosis (1 paper, 2024). Steatosis is a term used to denote lipid accumulation within hepatocytes. "To explore the potential role of hLMR1 and mLMR1 in liver disorders, we conducted a rescue assay in mice fed with a high-fat diet, which is known to induce hepatic steatosis." (PMID 39372743, 2024). "Given the elevated expression of h/mLMR1 in humans and mice with hepatic steatosis, the PABPC1-binding motif on hLMR1 emerges as a potential non-conserved human drug target whose functions can be fully validated in a physiologically relevant setting before clinical studies." (PMID 39372743, 2024).
nonalcoholic fatty liver disease (1 paper, 2024). "Additionally, hLMR1 was found to be up-regulated in livers of patients with nonalcoholic fatty liver disease (NAFLD), and mLMR1 was induced by high-fat diet feeding, suggesting a similar regulation of both lncRNAs in liver metabolic disorders." (PMID 39372743, 2024).
Obesity (1 paper, 2023). Accumulation of substantial excess body fat. "They managed to identify LINC01018 as an obesity-associated lncRNA, and hLMR1 promotes the transcription of cholesterol biosynthetic genes." (PMID 36707678, 2023).
HLMR1 also shares sentences with these, for which no sentence is quoted: liver disorder (1 paper); steatosis (1).